RNU6-682P (RNA, U6 small nuclear 682, pseudogene)
Gene: Small nuclear RNA gene on chromosome 8 (8,895,813 to 8,895,918, forward strand). Ensembl gene ENSG00000200713.
Homologues: Orthologues: chimpanzee U6 (98% identical), mouse Gm22753 (80% identical), guinea pig U6 (44% identical). Paralogues in human: RNU6-38P (84% identical), RNU6-242P (83% identical), RNU6-1031P (81% identical), RNU6-1084P (81% identical), RNU6-1124P (81% identical), RNU6-1145P (81% identical), RNU6-116P (81% identical), RNU6-1316P (81% identical), RNU6-28P (81% identical), RNU6-326P (81% identical), RNU6-43P (81% identical), RNU6-468P (81% identical), and 1288 more.